C1orf226 (chromosome 1 open reading frame 226)
Synonyms: FLJ13137
Tractability: PROTAC: ubiquitination databases record sites on it.
Gene: Protein-coding gene on chromosome 1 (162,378,841 to 162,386,812, forward strand). Ensembl gene ENSG00000239887.
Subcellular location (Human Protein Atlas): Nucleoplasm
Gene Ontology:
Molecular function: protein binding
Genetic constraint (gnomAD): Loss-of-function variants: 8 observed, 13.24 expected, observed/expected ratio (o/e) 0.6, 90% interval 0.35 to 1.09. The upper end of that interval is the gene's LOEUF score, 1.09, which puts it in group 4 of 6, group 1 being the genes least tolerant of losing a copy. Missense variants: 313 observed, 326.43 expected, observed/expected ratio (o/e) 0.96, 90% interval 0.87 to 1.05. Synonymous variants: 125 observed, 136.17 expected, observed/expected ratio (o/e) 0.92, 90% interval 0.79 to 1.07.
Homologues: Orthologues: macaque NOS1AP (95% identical), guinea pig C1orf226 (67% identical), dog NOS1AP (65% identical), zebrafish nos1apa (43% identical), tropical clawed frog nos1ap (38% identical), Caenorhabditis elegans dyc-1 (15% identical), Drosophila melanogaster Dab (12% identical), Drosophila melanogaster CG42673 (10% identical), Drosophila melanogaster CG8312 (4% identical), Drosophila melanogaster numb (4% identical), Caenorhabditis elegans num-1 (4% identical), Caenorhabditis elegans dab-1 (3% identical), and 3 more. Paralogues in human: NOS1AP (9% identical), GULP1 (9% identical), NUMB (7% identical), NUMBL (7% identical), DAB1 (7% identical), DAB2 (7% identical), FAM43A (6% identical), LDLRAP1 (3% identical), MAPK8IP1 (3% identical), FAM43B (2% identical), MAPK8IP2 (1% identical).
Diseases named in the same sentence as C1orf226 in open-access papers:
C1orf226 is named in the same sentence as 1 disease in open-access papers, as found by Europe PMC text mining. Sharing a sentence is not in itself a finding about the gene and the disease. The quoted sentences say what the papers report.
tumor (1 paper, 2023). "In the case analyses, genes such as TMEM92 and C1orf226 showed consistent expression in pretreatment surgically resected tumor tissues, and posttreatment blood may be indicators of GBM." (PMID 36697401, 2023).